ENSG00000252517
Synonyms: LOC124906142
Gene: Small nucleolar RNA gene on chromosome 2 (194,664,107 to 194,664,174, reverse strand). Ensembl gene ENSG00000252517.
Gene Ontology:
Biological process: RNA processing
Cellular component: nucleolus
Homologues: Paralogues in human: SNORD59A (68% identical).